ATM (ATM serine/threonine kinase)
Diseases named in the same sentence as ATM in open-access papers (continued):
Sharing a sentence is not in itself a finding about the gene and the disease.
cancer (continued). "Together, these data demonstrate that cancer cells surviving treatment with matched targeted therapies exhibit DNA double strand breaks and consequent ATM activation." (PMID 35353542, 2022). "Targeting ATM with an ATM inhibitor such as KU60019 is a promising strategy to inhibit tumor cell growth in antitumor therapy for several cancer types." (PMID 35795059, 2022). "A comprehensive understanding of this field is required for characterizing the pathogenesis of A-T and other ATM-related diseases such as cancer." (PMID 34628594, 2022). "For instance, shared clonal mutations in driver genes such as ATM, ATRX, BRCA1/2, DAXX, MSH3, and MSH6 are associated with aberrations in major cellular signaling pathways like Pathways in cancer, DNA damage response, and regulation of cell cycle." (PMID 36140756, 2022). "Among cancer predisposing genes, mutations in BRCA2 and ATM play a role in PDAC progression, whilst the role of other genes remains to be defined." (PMID 35805011, 2022). "Since the cloning of the ATM gene in 1995, a number of studies have demonstrated that ATM plays key roles in DNA damage response and suppression of cancer at early stages." (PMID 35008949, 2022). "Many studies have reported essential roles played by HER2 and ATM in bladder carcinogenesis individually." (PMID 36056635, 2022). "Here, we report that the coordinated actions of MYC, PARP1, and ATM assist cancer cells in acquiring cisplatin resistance by BIN1 deficits." (PMID 34948122, 2021). "The analysis of patient mutations and mouse models revealed that the presence of inactive ATM, named ATM kinase-dead, is more cancer prone and lethal than its absence." (PMID 34771661, 2021). "We find that 233 of the 961 ATM and 147 of the 746 ATR residues mutated in cancer are conserved in the budding yeast ATM/ATR proteins Tel1 and/or Mec1." (PMID 33742106, 2021). "There have been a number of studies demonstrating that the blockage of ATM activity confers an increased vulnerability to DSBs in various types of cancers." (PMID 34545188, 2021). "Since the ATM protein plays an important role in DNA repair through the activation of enzymes that fix the broken strands, its biology is of interest in cancer research." (PMID 34068084, 2021). "Cancer cell lethality was significantly enhanced when ATM was inhibited in combination with DUTi and epirubicin, but not with ATR inhibition." (PMID 33824328, 2021). "Cancers with defective ATM protein or aberrations of the MRE11A-RAD50-NBN complex are included in BRCAness." (PMID 34639169, 2021). "Among the conserved, four ATM (G2083, G2765, E2868, and S3027) and three ATR (C607, E2378, and G2530) residues are mutated in cancer." (PMID 33742106, 2021). "A recent paper identified the DNA double-strand break signaling kinase ataxia-telangiectasia mutated (ATM) and its downstream target checkpoint kinase 2 (Chk2) as regulators of Aurora B recruitment to the midbody center in human cancer cells." (PMID 34943860, 2021). "This study provides insights into the genotype-phenotype relationships in ATM/ATR and their cancer-associated variants." (PMID 33742106, 2021). "Higher responses were evident in ATM-deficient cancers for the carboplatin group, and in BRCA1/2-mutated cancers for the olaparib-treated group where responses were independent of ATM status." (PMID 33672884, 2021).
cancer (continued). "In this review, we will cover the major features, roles, and signaling pathways of ATM, especially its diverse roles in tumor suppression and cancer progression." (PMID 34070860, 2021). "It is proposed that polyphenol resveratrol (RSV) provokes a differential stress response and radiosensitizes cancer cells via interference with ATM-signaling and apoptosis cascade." (PMID 34041023, 2021). "The polymorphisms RAD51/G135C, ATM/P1054R, and CHEK2/T470C were selected because they were associated with many cancers, such as prostate, breast, head and neck cancer, and leukemias." (PMID 33778923, 2021). "Because ATM expression is known to be induced also in response to hypoxic stress, it has been suggested that ATM also plays pivotal roles in the radioresistance of cancer cells under hypoxic conditions." (PMID 34135469, 2021). "Gaul conducted in vitro experiments to identify the molecular mechanism of action of bendamustine, which can kill cancer cells, and found that bendamustine, as an ATM promoter, can induce G2 cell cycle arrest." (PMID 34565365, 2021). "However, it remains controversial whether DDR inhibitors could be beneficial for cancer therapy because ATM deficiency can potentially lead to oncogene-induced proliferation, as shown in in vitro transformation experiments and also in the cancer predisposition of A-T patients." (PMID 34069817, 2021). "This drug induced tumor senescence in breast, lung, and colon carcinoma cell lines and verified the ATM/ATR signaling pathway to be constitutively active in cancer cells." (PMID 33912571, 2021). "One potential explanation for these observations is that compensatory ATR activity can mitigate any HRD phenotype in ATM mutant cancer." (PMID 34572943, 2021). "NF-KB activation by ATM additionally increases cancer cell survival, blocks apoptosis, and facilitates Epithelial-Mesenchymal Transition, as well as cancer cell migration and metastasis." (PMID 34070860, 2021). "The most dysregulated genes were related with the signaling pathways such as AKT-MTOR, CYCLIN D1, KRAS, EIF4E, RB, and ATM, which play an essential role in cancer cell proliferation, survival, and response to external stimuli." (PMID 34944712, 2021). "One such example is that of the early response gene ATM whose role in mediating cancer resistance has been well-elucidated and thus several of the ATM inhibitors are under different phases of the clinical trials." (PMID 33777104, 2021). "The ATM inhibitor also strongly sensitized all cancer cell lines investigated here to X-ray radiation; however, only H460 was significantly sensitized to α-radiation." (PMID 34853427, 2021). "In summary, ATM is overexpressed in a variety of radiation‐resistant tumors, and the ATM pathway regulates cell cycle checkpoints to make cancer cells resistant to radiotherapy after IR‐induced DNA damage." (PMID 34766149, 2021). "To examine this notion, we have found that the selective ATM kinase inhibitor KU55933 can inhibit DNA damage-induced ATM signaling and decrease cell viability of cancer cells." (PMID 34068585, 2021). "Anti-cancer therapy based on the personalized ATM and BRCA1 expression can probably improve the outcome of HNC patients." (PMID 34068585, 2021). "On the other hand, ATM has multiple functions in cancer development, such as cell cycle checkpoint modulation, DNA double-strand break repair, metabolic regulation, migration, and chromatin remodeling." (PMID 33800556, 2021).
cancer (continued). "In line with this, RBM6 depletion renders cancer cells vulnerable to ATM and PARP inhibition and exhibits pronounced sensitivity to cisplatin." (PMID 34718714, 2021). "In contrast, the combination of DUTi plus FUdR significantly enhanced cancer cell lethality with both ATM and ATR inhibition." (PMID 33824328, 2021). "At present, studies on SNPs in ATM gene have primarily focused on cancer and lifespan, and limited information regarding the specific effects of mutant rs189037 in ATM gene on cardiac structure and human longevity is available." (PMID 34124196, 2021). "For instance, cancer cells with DDR dysfunction, such as mutations in BRCA1/2 or ATM, show high levels of cytosolic DNA, which activates the STING pathway and innate immune response correlated with a durable response to ICIs." (PMID 34026622, 2021). "Perhaps, those cancer cells have developed mechanisms to escape ATM-induced cell cycle arrest and apoptosis." (PMID 34070860, 2021). "Cancer patients with impaired DDR pathways (including the ATM pathways) generally respond better to cisplatin." (PMID 34948122, 2021). "This compound was further found to synergize with ATR (ataxia-telangiectasia mutated (ATM) and Rad3-related protein kinase) inhibitor VE-821 and induce a synthetic lethal interaction in cancer cells, which had been described before in RNA interference screens." (PMID 33941852, 2021). "A single unrepaired DSB in a cell can be cytotoxic, additionally mutations or down-regulation of DNA repair proteins, associated with the repair of DSBs, are strongly linked with inherited cancer risk (BRCA1, BRCA2, ATM)." (PMID 33669398, 2021). "We find that 42% and 32% of the conserved ATM and ATR residues mutated in cancer are in the kinase domains, representing approximately a threefold and twofold enrichment, respectively." (PMID 33742106, 2021). "Many reports linked increased ATM and DDR signaling with the survival of cancer cells after chemotherapy, rendering this pathway an attractive target for overcoming cancer chemoresistance." (PMID 34839359, 2021). "Numerous studies during the past three decades show that ATM is a central coordinator of the DNA-damage response and plays a vital role in maintaining genomic integrity and suppressing cancer at early stages." (PMID 34070860, 2021). "In this study we observed significantly increased micronucleus frequency after co-treatment of α-radiation with ATM inhibitors in H1299 and 22Rv1 cancer cell lines." (PMID 34853427, 2021). "We conducted a similar multivariate regression analysis for somatic mutations, and identified 24 significant associations in five (i.e., BRCA1, BRCA2, ATM, ATR, CHEK2) genes and higher HRD (FDR < 0.05) across cancer types." (PMID 34572800, 2021). "KU‐55933 (Ku) is an ATM inhibitor that has been used to treat a variety of cancers, functioning by inducing mitochondrial superoxide production and thereby synergistically driving apoptotic cell death." (PMID 33742560, 2021). "This review focuses on addressing major characteristics, signaling pathways and especially the diverse roles of ATM in cellular homeostasis and cancer development." (PMID 34070860, 2021). "Inhibition of ATM and consequent accumulation of unrepaired breaks leading to increased cell death provides the rationale for developing this combination for cancer treatment." (PMID 34429505, 2021). "The cancer-associated residues are next to the kinase domain residues ATR G2375 and ATM G2925, respectively, providing further support for the functional relevance of the FAT kinase domain interface int the ATM, ATR, and Mec1 enzyme complexes." (PMID 33742106, 2021).
cancer (continued). "The ATM/ATR-derived centrosome clustering of centrosome amplified cancer cells, therefore provides a new way to study tumor cell resistance to DNA damaging therapy, CIN, and tumor recurrence." (PMID 33397932, 2021). "Inhibition of ATM expression can enhance the sensitivity of cancer cells to IR by delaying DNA DSB repair, preventing Nuclear factor‐κB (NF‐κB) translocation, inhibiting phosphorylation of p38 and inducing of cJun N terminal kinase (JNK) activity." (PMID 34766149, 2021). "In line with this, MSC-1 harbored mutations in many drivers, such as ATM, BRAF, and HMCN1, which play vital roles in the tumorigenesis and development of many cancers." (PMID 33959500, 2021). "Se has also been reported to activate ATM/ATR, but this activation is associated with Se-induced DNA damage in cancer cells." (PMID 33875618, 2021). "The significantly altered canonical pathways include a number of cancer pathways, including Cell Cycle: G1/S Checkpoint Regulation, ATM Signaling, Antiproliferative Role of TOB in T Cell Signaling, PI3K/AKT Signaling, Wnt/β-catenin and Wnt/Ca2+ pathways." (PMID 34659334, 2021). "Among, the positive link between ATM mutations and ICB benefits in BLCA was recently demonstrated, and this link was further verified based on 7 cancers in our study." (PMID 34747718, 2021). "Numerous somatic mutations, including cancer-associated mutations in ARID1A, ATM, CDH4, NRAS, and PIK3CA, were shared among the epithelium from the uterine endometrium, endometriotic lesions distant from and adjacent to the carcinoma, and the carcinoma itself." (PMID 33809880, 2021). "ATM inhibition enhances the sensitivity of cancer cells to radiation therapy, whereas, phosphorylated ATM protein increases the radiation resistance of cancer cells and correlates with poor prognosis of cancer patients." (PMID 32329754, 2020). "Intriguingly, mRNA expression of ATM and Mre11 was upregulated in tumor tissue compared with matched samples in some cancer types but downregulated in other cancer types." (PMID 32111912, 2020). "Consistently, PER1 overexpression and subsequent activation of downstream ATM-Chek2 signalling has been proved to suppress the growth of multiple human cancer cell lines by inducing G2/M cell cycle arrest." (PMID 32429928, 2020). "Studies have reported activation of ataxia-telangiectasia mutated (ATM) and liver kinase B1 (LKB1) as alternative anti-cancer mechanisms of metformin." (PMID 33198356, 2020). "The very young age at cancer onset of our case and the recurrent detection of ATM deleterious alterations in MBC patients suggest that the involvement of this gene in the predisposition to the disease should be further investigated in larger case series." (PMID 32365798, 2020). "Recently, inhibiting the DDR pathway has become a common treatment strategy in many cancers, and the ATM signaling pathway is known to play an important part in the development of breast cancer, germ cell carcinoma and other cancers." (PMID 32922441, 2020).
cancer (continued). "As a histone modifier, KAT8 has been shown to physically interact with MLL1 and regulate known cancer drivers ATM and TP5348–51." (PMID 32024818, 2020). "The differences in DNA repair can be important for immunotherapy because PD-L1 expression in cancer cells is upregulated in response to DNA double-strand breakage, through the ATM/ATR/Chk1 kinase pathway." (PMID 33080914, 2020). "We propose that cancer cells develop elevated radioresistance through enhanced DNA damage repair efficiency mediated by increased ATM expression." (PMID 32174787, 2020). "This study identifies a novel lncRNA, HITT, that plays an essential role in inhibiting ATM activity and sensitizes cancer cells to DNA-damaging agents." (PMID 32203529, 2020). "Despite these controversies, consistent ATM variants (ATM p.P1054R-rs1800057- and rs149711770) were recently described in families with FNMTC and other cancers (as kidney, lung, stomach, and prostate)." (PMID 33218058, 2020). "Inhibition of endogenous Per1 expressionresulted in the abrogation of the ATM/Checkpoint kinase 2 (Chk2) checkpoint pathway and led to less DNA damage-induced apoptosis of cancer cells." (PMID 32437452, 2020). "Mutations in the human Ataxia Telangiectasia Mutated (ATM) gene lead to a variety of pathologies, including increased risk of certain cancers, increased risk of infections, problems with motor control, and neurodegeneration." (PMID 32357532, 2020). "On the other hand, targeting DDR enhances the therapeutic effects of anti-cancer chemotherapy, which led to the development of specific kinase inhibitors for ATM, ATR and DNA-PKcs." (PMID 32015826, 2020). "This was confirmed using ATM inhibiting drugs, which demonstrates a promising new utility for ATM inhibitors in cancer therapy." (PMID 36046263, 2020). "The results showed that ATM, CHD4, FAT1, KMT2D, MED12, NF2, and SUFU were the most frequently mutated cancer-related genes." (PMID 33193598, 2020). "For example, BRCA1-mutated tumor cells, which also harbor 53BP1 inactivations, show resistance to PARPi, while this phenotype depends on ATM activity, which makes these cancer cells specifically vulnerable to ATM inhibition." (PMID 33299637, 2020). "Several other compounds have been produced such as KU-55933, KU-60019 and KU-59403 that are in pre-clinical studies, therefore targeting ATM is a promising strategy for cancer treatment." (PMID 32932697, 2020). "In pre-clinical trials, transient inhibition of ATM led to radiosensitization or chemosensitization in vivo and in vitro, thus it is possible that ATM inhibitors strengthen the effects of anti-cancer drugs or irradiation." (PMID 32157166, 2020). "Several highly selective small molecule inhibitors of ATM have entered clinical trials in patients with advanced cancers." (PMID 32203529, 2020). "MDC1 silencing in combination with radiation or chemotherapeutic agents presents a rational strategy for the treatment of ATM proficient cancers, which primarily depend on the ATM-Chk2 pathway activation for the repair of double strand DNA breaks." (PMID 32160908, 2020). "SIRT7 seems to have a dual role in cancer cells by targeting substrates (e.g., H3K18ac, ATM, and SMAD4)." (PMID 32404984, 2020).